DPP4 (dipeptidyl peptidase 4)
Diseases named in the same sentence as DPP4 in open-access papers (continued):
Sharing a sentence is not in itself a finding about the gene and the disease.
kidney disease (52 papers, 2013 to 2026). "In the 5/6 nephrectomy model of kidney disease, restoration of megalin expression and amelioration of tubular and glomerular proteinuria by DPP4 inhibition was accompanied by suppression of the kidney disease-associated upregulation of renal Ang II20." (PMID 40604004, 2025). "It was observed that elderly patients and patients with renal disease were associated with a prescription of DPP-4 inhibitors as the index treatment." (PMID 31695754, 2019). "In 53,096 initiations of SGLT2 inhibitor treatment compared with 88,404 initiations of DPP4 inhibitor/sulfonylurea treatment, there was a 42% lower relative risk of kidney disease progression with SGLT2 inhibitors (HR 0.58; 95% CI 0.48, 0.69), consistent with a previous trial meta-analysis." (PMID 41206830, 2026). "This case indicates that DPP-4 inhibitors can cause not only skin lesions but also renal disease." (PMID 38055184, 2024). "In recent years, an increasing number of studies have focused on the potential renoprotective effects of DPP-4 inhibitors in T2DM-related kidney disease." (PMID 41601976, 2026). "A limitation of using linagliptin in the research is that it is challenging to distinguish the direct role of DPP4 in kidney disease." (PMID 40607249, 2025). "This is the first report that DPP-4 activity was increased in human various kidney diseases by in situ staining." (PMID 32948146, 2020). "Our future goal is to expand the clinical application of DPP-4 inhibitors to other kidney diseases in addition to DN." (PMID 32948146, 2020). "Hazard of observing kidney disorders after treatment with sulfonylureas, DPP-4 inhibitors, or thiazolidinediones was equally likely." (PMID 30646124, 2018). "The precise mechanism is yet to be identified; however, it appears possible that renal DPP-4 activity does indeed decrease in some models of renal diseases." (PMID 28118775, 2017). "Studies have indicated that DPP-4 inhibitors can reduce albuminuria, a key marker of kidney damage, and may slow the progression of kidney disease." (PMID 39768866, 2024). "Another study investigating the role of DPP-4 in kidney disease suggested Linagliptin as an inhibitor of podocyte growth, which could reduce albuminuria with Linagliptin in the long term." (PMID 35610696, 2022). "Therefore, we investigated the effects of a novel DPP-4 inhibitor, DA-1229, on the progression of renal disease in an experimental cyclosporine nephrotoxicity model." (PMID 33803842, 2021). "The role of DPP-4 inhibitors in renal disease is not fully understood." (PMID 34697593, 2021). "In the present study, we evaluated DPP-4 activity in the glomeruli in human kidney diseases." (PMID 32948146, 2020). "Other studies found a correlation between increased DPP-4 activity and kidney diseases." (PMID 32948146, 2020). "Similarly, the potential beneficial effects of DPP-4 inhibitors, including linagliptin, in preventing and treating progression of kidney disease in patients with T2DM is supported by retrospective analyses of clinical trials." (PMID 29669555, 2018). "Therefore, the roles of DPP4 in kidney disease require further investigations." (PMID 40607249, 2025). "Thus, DPP-4 affects systemic physiological functions such as glucose metabolism, cellular signaling, and oxidative stress, suggesting that renal DPP-4 activity may be involved in the progression of kidney diseases." (PMID 32948146, 2020). "Therefore, a targeted therapy aimed at inhibiting DPP-4 activity or activating GLP-1R signalling may be a prospective approach in the management of renal disorders such as renal microcirculation lesion-induced fibrosis." (PMID 29607314, 2018). "Over a median follow-up of 1·4 years (IQR 0·6-3·0), kidney disease progression occurred in 187 (0·9%) of 20 039 individuals who initiated a GLP-1 receptor agonist and 189 (1·4%) of 13 620 who initiated a DPP-4 inhibitor or sulfonylurea." (PMID 42109572, 2026).
kidney disease (continued). "Medications, like glucagon-like peptide-1 receptor agonists (GLP-1 RA) and dipeptidyl peptidase 4 (DPP-4) inhibitors, slow albuminuria, while SGLT-2 inhibitors reduce renal disease progression and the need for dialysis." (PMID 39941397, 2025). "Using a large Israeli database, we assessed whether long-term use of SGLT2is versus dipeptidyl peptidase 4 inhibitors (DPP4is) is associated with kidney benefits in patients with type 2 diabetes overall and in those without evidence of cardiovascular or kidney disease." (PMID 37382938, 2023). "GLP-1 and dipeptidyl-peptidase 4 (DPP-4) inhibitors can protect against proteinuria and renal disease progression." (PMID 30823876, 2019). "In contrast to other CVOTs in the DPP-4 inhibitor class, the CARMELINA trial included a substantial proportion of patients with T2DM; 74% had prevalent kidney disease." (PMID 30876392, 2019). "Linagliptin, in particular, is unique among DPP-4 inhibitors in that it does not require dose adjustment at any stage of renal impairment, making it a viable option for patients with advanced kidney disease." (PMID 39768866, 2024). "We aimed to test the long-term association between use of SGLT2is, specifically empagliflozin, compared with dipeptidyl peptidase 4 inhibitors (DPP4is), and kidney outcomes, with specific emphasis on populations without evidence of cardiovascular and kidney disease." (PMID 37382938, 2023). "First, unlike other DPP-4 inhibitors that are excreted largely in urine, linagliptin is mainly eliminated by a biliary route and therefore does not require dose adjustment in patients with kidney disease." (PMID 29669555, 2018).
hematological malignancies (14 papers, 2015 to 2025). "However, the diagnostic and prognostic value of (s)CD26/DPP4 in most hematologic malignancies is still a matter of debate." (PMID 34885056, 2021). "CD26/dipeptidylpeptidase IV (DPP-4) is a membrane-bound multifunctional protein expressed in many primary solid tumors and in hematological diseases." (PMID 35205639, 2022). "Early studies also suggested a role of CD26/DPP4 in hematological malignancies." (PMID 34885056, 2021). "Moreover, whereas some studies already suggest CD26/DPP4 as a therapeutic target in solid cancers, data regarding hematologic malignancies are still missing." (PMID 34885056, 2021).
infectious disease (14 papers, 2010 to 2024). A disorder directly resulting from the presence and activity of a microbial, viral, or parasitic agent in humans. "In this study, we investigated a potential risk of infectious diseases with the use of two major oral antidiabetics, DPP-4 inhibitors and SGLT-2 inhibitors." (PMID 37891260, 2023). "Considering their life-long dependency on hypoglycemic therapy to prevent CV and metabolic complications due to T2DM, there is a strong need to investigate potential infectious disease risks linked to major antidiabetic drug classes, such as DPP-4 inhibitors and SGLT-2 inhibitors." (PMID 37891260, 2023). "This review aims to summarize the roles of DPP4 and its inhibitors in infectious lung diseases and non-infectious diseases to provide new insights for clinical physicians." (PMID 34955820, 2021). "The current study findings offer further assurance that DPP-4 inhibitors are safe to be used together with insulin in progressed T2DM patients in terms of infectious disease risks, whereas the link between SGLT-2 inhibitors and genital infection risks was also confirmed in our study." (PMID 37891260, 2023). "Previous clinical studies found that inhibition of DPP4 by specific DPP4 inhibitors resulted in slightly increased rates of infectious diseases and might impair T cell response and function, while T cell frequencies were not affected." (PMID 32946499, 2020). "Because of the host restriction conferred by the binding of the MERS-CoV spike protein to its receptor, dipeptidyl peptidase 4 (DPP4), small animal models that are routinely used to conduct infectious disease research are not naturally susceptible to MERS-CoV infection." (PMID 28318484, 2017).
retinopathy (14 papers, 2015 to 2025). "The present study further confirmed that, among insulin-treated patients with T2D, GLP-1 RA therapy was associated with a significantly lower risk of sight-threatening retinopathy compared with DPP-4 inhibitors." (PMID 41011236, 2025). "As low glycemia is one of the causes of retinopathy, metformin may have been preferred over DPP-4 inhibitors in patients with microvascular disease." (PMID 31695754, 2019). "Theoretically, linagliptin may exert adverse effects on the neurovascular unit because DPP-4 inhibition may promote the development of proliferative retinopathy." (PMID 40308768, 2025). "Theoretically, linagliptin could also have adverse effects on the neurovascular unit, since DPP4 inhibition may promote the development of proliferative retinopathy." (PMID 27942008, 2016). "By contrast, our previous cohort study found no significant increase in the risk of sight-threatening retinopathy with GLP-1 RA use compared with non-use, and in fact demonstrated a significantly lower risk compared with DPP-4 inhibitor use." (PMID 41011236, 2025).
respiratory diseases (13 papers, 2019 to 2026). "This meta-analysis systematically evaluated the impact of three major classes of novel glucose-lowering drugs—SGLT2 inhibitors, GLP-1 receptor agonists, and DPP-4 inhibitors—on the risk of seven clinically relevant respiratory diseases." (PMID 41567683, 2025). "DPP4 inhibitors can not only improve respiratory diseases, such as acute respiratory distress syndrome and ILDs, but also cardiovascular diseases, such as left heart dysfunction and atherosclerosis." (PMID 38255821, 2024). "CD26/Dipeptidyl peptidase-4 (DPP4) is expressed in lung constituent cells and may be related to the pathogenesis of various respiratory diseases." (PMID 38255821, 2024). "Li and McCray utilized human DPP4 knock-in (hDPP4 KI) mice to infect MERS-CoV, but the transgenic mice still did not display respiratory disease after MERS-CoV infection." (PMID 38252647, 2024).
kidney (10 papers, 2014 to 2026). "Katagiri and others have also revealed that the effect of DPP-4 inhibitor was mediated by glucagon-like peptide-1 (GLP-1), suggesting that any medicines which increase the level of GLP-1 could prevent cisplatin-induced kidney injury." (PMID 32084231, 2020).
immune disorders (9 papers, 2007 to 2026). "Furthermore, MERS-CoV, which is 50% similar to the genetic sequence of SARS-CoV-2, has been suggested to invade T cells by binding to dipeptidyl peptidase 4 (DPP4) as its cellular receptor and activate the nuclear factor kappa B pathway, leading to the immunity disorders." (PMID 33002109, 2020). "Clinical and experimental study over the past 30 years has clearly demonstrated that the DPP4/CD26 pathway is involved in a variety of physiological processes and immune system diseases." (PMID 33928135, 2021).
inflammation (8 papers, 2016 to 2024). Aberrant reaction of the microcirculation characterized by movement of fluid and leukocytes from the blood into extravascular tissues. "Interestingly, augmented IL9 along with low CD96 and DPP4 expression observed in UC relative to CD mimics a Th9 pro-inflammatory profile associated with chronic intestinal inflammation in mice." (PMID 31191543, 2019). "They found that the levels of palmitic acid and soluble dipeptidyl peptidase 4 (DPP4), a mediator of eosinophilic airway inflammation, are elevated in the BAL fluid of obese asthmatics as compared to lean asthmatics." (PMID 37893170, 2023). "Although DPP-4 was recently reported to be involved in pathologic features of asthmatic airway inflammation, cell proliferation, and fibronectin production, there are few studies concerning the role of DPP-4 in pulmonary vascular function." (PMID 29037205, 2017). "Given the strong linkage between circulating DPP-4, adipose inflammation, and NAFLD, △DPP-4 may reflect certain key mechanisms of the “Twin Cycle “, suggesting the potential for long-term remission post-SIIT." (PMID 38476668, 2024). "Although we observed a significant role of DPP4 in IL-13-induced airway eosinophilic inflammation, the contribution of DPP4 to airway eosinophilic inflammation mediated by IL-13 and PA remains unclear." (PMID 37287831, 2023). "DPP4 may be involved in the pathologic features of asthmatic airway inflammation and cell proliferation and FN production." (PMID 26975422, 2016).
neurodegenerative disease (7 papers, 2016 to 2023). A disorder of the central nervous system characterized by gradual and progressive loss of neural tissue and neurologic function. "Glucagon-like peptide-1 (GLP-1) was reported as a potential candidate in modifying neurodegenerative diseases as a promising antiparkinsonian effect of dipeptidyl peptidase (DPP)-4 inhibitors (Gliptins) by exerting a neuroprotective effect in PD animal models." (PMID 29895906, 2018). "GLP-1 is a potential candidate in modifying neurodegenerative diseases as a promising antiparkinsonian effect of DPP-4 inhibitors." (PMID 29895906, 2018).
neurological disorders (7 papers, 2015 to 2025). "Epidemiological data have convincingly demonstrated that the most evident risk factors for BP are certain neurological diseases and the use of dipeptidyl peptidase 4 (DPP4) inhibitors (gliptins)." (PMID 35958564, 2022). "Additionally, the concentrations were lower than those in individuals with neurological disorders or DPP-4 deficiency." (PMID 27680716, 2016). "Incretin-based treatments, including GLP-1 and GIP analogues as well as DPP-4 inhibitors like saxagliptin, have been shown to reduce brain inflammation and oxidative stress in various neurological disorders." (PMID 39904872, 2025). "The DPP4 locus is flanked by the GCG gene (encoding proglucagon, the source of glucagon, GLP-1, and GLP-2) and the SLC4A10 gene, both of which have some shared characteristics, such as involvement in neurological disorders." (PMID 40904650, 2025). "So a unique mechanism of action of DPP4 inhibitors may be used to improve the cognitive skills in the AD and other neurological diseases." (PMID 35468904, 2022). "In recent years, incretin-based therapies, including DPP-4 inhibitors and GLP-1 analogues, have been explored as treatments for multiple neurological diseases." (PMID 39904872, 2025).
heart diseases (6 papers, 2011 to 2025). "As diastolic dysfunction and stiffening in MetS patients are associated with increased circulating DPP‐4 levels, we investigated whether the clinically approved DPP‐4 inhibitor linagliptin reduces left ventricular stiffness in MetS‐induced cardiac disease in obese ZSF1 rats." (PMID 33295687, 2021). "As diastolic dysfunction and stiffening in MetS patients are associated with increased circulating dipeptidyl peptidase‐4 (DPP‐4) levels, we investigated whether the clinically approved DPP‐4 inhibitor linagliptin reduces left ventricular stiffness in MetS‐induced cardiac disease." (PMID 33295687, 2021). "The potential antifibrotic effects of DPP-4 inhibitors could provide an additional benefit for patients with CKD and heart diseases that very often accompany T2D and may provide new therapy options for this class of drugs." (PMID 22125632, 2011).
psychiatric disorder (5 papers, 2018 to 2025). A disorder characterized by behavioral and/or psychological abnormalities, often accompanied by physical symptoms. "It is worth noting that some studies reported potential non-vaccine triggers, such as neurological or psychiatric disorders, use of DPP-4 inhibitor, polypharmacy, or a history of COVID-19 infection." (PMID 38793716, 2024).
intestinal disease (4 papers, 2018 to 2024). "The Dipeptidyl peptidase-4 (DPP-4) activity influences metabolic, behavioral and intestinal disorders through the cleavage of key hormones and peptides." (PMID 30186247, 2018). "Furthermore, the review underscores the bidirectional relationship between DPP4 and the gut microbiota, where DPP4 activity affects microbial composition, and, reciprocally, gut microbiota dysbiosis influences DPP4 expression and function, perpetuating intestinal disease." (PMID 39684563, 2024). "DPP4 expression in the intestine is the highest among that of all organs, speculated to be widely distributed in the intestinal tract and closely related to the occurrence and development of various intestinal diseases." (PMID 31827684, 2019).
bacterial infections (3 papers, 2019 to 2022). "The role of Dpp4 and Hspg2 in bacterial infections has not been investigated." (PMID 36054235, 2022).
gastrointestinal disease (3 papers, 2017 to 2024). A disease that occurs in the gastrointestinal system, excluding the hepatobiliary system. "Our study investigated the causal relationship of seven common antidiabetic drug targets–metformin, GLP-1 receptor agonists, SGLT2 inhibitors, DPP-4 inhibitors, insulin and its analogs, thiazolidinediones, sulfonylureas and alpha-glucosidase inhibitors–on various gastrointestinal diseases." (PMID 38918852, 2024). "In addition to the regulation of nutrient metabolism, the emerging role of GLPs and their degrading enzyme dipeptidyl peptidase-4 (DPP-4) in gastrointestinal diseases has gained increasing attention." (PMID 29270177, 2017).
peripheral neuropathy (3 papers, 2020 to 2024). A disorder affecting the peripheral nervous system. "It has been reported that DPP-4 inhibitors have protective effects on central and peripheral neuropathies, including Parkinson’s disease, Alzheimer’s disease, and diabetic neuropathy." (PMID 32317735, 2020). "However, the protective efficacy of DPP-4 inhibitors on chemotherapy-induced peripheral neuropathy has not been previously published." (PMID 32317735, 2020).
vasculopathy (3 papers, 2021 to 2024). "Taken together with the findings of this present study, the effects of genetic and pharmacological DPP4 inhibition could differ in the pathogenesis of vasculopathy in PH, depending on the causes and/or species, and further studies are required." (PMID 39684311, 2024). "We are the first group to provide new prevention and treatment strategies for DPP-4 inhibitors in chronic rejection-induced vasculopathy." (PMID 34072966, 2021). "Previous, we have demonstrated that dipeptidyl peptidase-4 (DPP-4) inhibitor lowers OAT vasculopathy in rats through direct increase in GLP-1 activity, and regulates SDF-1α levels and EPCs function." (PMID 34072966, 2021).
benign neoplasm (2 papers, 2016 to 2021). A neoplasm which is characterized by the absence of morphologic features associated with malignancy (severe cytologic atypia, tumor cell necrosis, and high mitotic rate). "We showed cardioprotective effects of the DPP4 inhibitor vilda in pressure-overloaded mouse heart induced by TAC." (PMID 33073318, 2021).
brain disorder (2 papers, 2019 to 2025). A disease affecting the brain or part of the brain. "Linagliptin, classified as a potent DPP4 inhibitor, may mitigate cerebral vascular pathology associated with T2D and other diseases related to abnormal vascular formation, potentially slowing or inhibiting brain disorder progression." (PMID 38860903, 2025).
gastrointestinal disorders (2 papers, 2015 to 2025). "An increase in the concentration of the DPP4 substrates GLP-1, GIP (also called Gastric Inhibitory Polypeptide), the Pituitary Adenylate Cyclase-Activating Polypeptide (PACAP) and oxyntomoduline has been related to gastrointestinal disorders." (PMID 39861115, 2025). "In accordance with our results, a meta-analysis reported that there was no increased incidence of gastrointestinal disorders in patients treated with DPP-4 inhibitors." (PMID 26500706, 2015).